LINC00877 (long independently transcribed non-coding RNA 877)
Gene: Long non-coding RNA gene on chromosome 3 (71,943,592 to 72,279,946, reverse strand). Ensembl gene ENSG00000241163.
Diseases named in the same sentence as LINC00877 in open-access papers:
LINC00877 is named in the same sentence as 2 diseases in open-access papers, as found by Europe PMC text mining. Sharing a sentence is not in itself a finding about the gene and the disease. The quoted sentences say what the papers report.
tumor (1 paper, 2022). "Based on this evaluation, LINC00877, SLC25A5-AS1, ILF3-DT, LRRC75A-AS1, LINC00324, CD27-AS1, ZFAS1, SNHG5, MIR762HG, and SNRK-AS1 were the top significantly downregulated tumor suppressor candidates in MCL cases." (PMID 36359790, 2022).
LINC00877 also shares sentences with these, for which no sentence is quoted: venous thromboembolism (1 paper).